OR2A12 (olfactory receptor family 2 subfamily A member 12)
Description:
Odorant receptor.
Synonyms: OR2A12P; OR2A16P
Tractability: Antibody: UniProt places it where antibodies can reach, with medium confidence; UniProt predicts a signal peptide or a membrane-spanning region; its Gene Ontology location is reachable by antibodies, with medium confidence.
Gene: Protein-coding gene on chromosome 7 (144,086,278 to 144,098,953, forward strand). Ensembl gene ENSG00000221858.
Subcellular location: Cell membrane
Pathways (Reactome):
Sensory Perception: Expression and translocation of olfactory receptors
Gene Ontology:
Molecular function: olfactory receptor activity; G protein-coupled receptor activity
Biological process: detection of chemical stimulus involved in sensory perception of smell; G protein-coupled receptor signaling pathway
Cellular component: plasma membrane; membrane
Genetic constraint (gnomAD): Loss-of-function variants: 2 observed, 1.38 expected, observed/expected ratio (o/e) 1.45, 90% interval 0.45 to 1.92. That is too few expected variants to judge how well the gene tolerates losing a copy. Missense variants: 377 observed, 388.71 expected, observed/expected ratio (o/e) 0.97, 90% interval 0.89 to 1.06. Synonymous variants: 153 observed, 158.15 expected, observed/expected ratio (o/e) 0.97, 90% interval 0.85 to 1.11.
Homologues: Orthologues: chimpanzee OR2A12 (98% identical), macaque OR2A12 (94% identical), mouse Or2a12 (85% identical), dog OR2A12 (85% identical), guinea pig OR2A12 (69% identical). Paralogues in human: OR2A5 (76% identical), OR2A14 (74% identical), OR2A2 (70% identical), OR2A1 (69% identical), OR2A42 (69% identical), OR2A25 (64% identical), OR2A7 (61% identical), OR2A4 (60% identical), OR7A10 (45% identical), OR4E2 (45% identical), OR1N1 (45% identical), OR7D4 (45% identical), and 116 more.